CAND1 (cullin associated and neddylation dissociated 1)
Diseases named in the same sentence as CAND1 in open-access papers (continued):
Sharing a sentence is not in itself a finding about the gene and the disease.
malaria (1 paper, 2018). Malaria is a serious and sometimes fatal disease caused by a parasite that commonly infects a certain type of mosquito which feeds on humans. "Likewise, although significant associations were seen between severe malaria and polymorphisms in seven additional genes (IL10, LPHN2 [ADGRL2], LOC727982, ARL14, RPS6KL1, CAND1, and GNAS), without further data their potential for translation remains elusive." (PMID 30033078, 2018).
prostate tumor (1 paper, 2020). "To summarize, we found that Cand1 expression is associated with prostate tumor aggressiveness and recurrence, and that targeting Cand1 reduces the viability and proliferative capacity of prostate tumor cells." (PMID 32059441, 2020).
renal cell carcinoma (1 paper, 2014). "CAND1 may also promote the progression of renal cell carcinoma through its interaction with carbonic anhydrase IX." (PMID 24997640, 2014).
renal failure (1 paper, 2014). "For the rest four hub genes, SRSF1, CAND1, SMURF1, and YWHAE, no previous report of their association with renal failure has been proposed before." (PMID 24997640, 2014).
squamous carcinomas (1 paper, 2017). "CAND1 represents an example, where high CN gain is associated with increased gene expression in adenocarcinomas but not in squamous carcinomas." (PMID 29112949, 2017).
steatosis (1 paper, 2023). Increased lipid within the cytoplasm of cells. "Hepatocyte-specific CAND1 knockout male mice showed increased steatosis in HFD-treatment and fasting state, while CAND1 overexpression male mice manifested the reverse phenotype." (PMID 37528093, 2023).
cancer (9 papers, 2016 to 2025). A tumor composed of atypical neoplastic, often pleomorphic cells that invade other tissues. "The authors identify that loss of SRPK1 sensitises cancer cells to indisulam treatment and loss of CAND1 confers resistance." (PMID 35534224, 2022). "Accumulative evidence demonstrates that CAND1 is upregulated in various cancers and regulates lipogenesis." (PMID 37837399, 2023). "In total, we analyzed 251 benign and 212 cancer areas from the local cohort of 95 patients on Cand1 expression and studied different expression patterns of Cand1 in tumor versus benign samples." (PMID 32059441, 2020). "Remarkably, Cand1 was significantly higher expressed in cancer cores compared to benign cores (p < 0.002)." (PMID 32059441, 2020). "Evidence has accumulated asserting the importance of cullin-RING (really interesting new gene) ubiquitin ligases (CRLs) and their regulator Cullin-associated neural-precursor-cell-expressed developmentally down-regulated 8 (NEDD8) dissociated protein 1 (Cand1) in various cancer entities." (PMID 32059441, 2020). "We demonstrate that suppression of androgen receptor (AR), cullin-associated and neddylation-dissociated 1 protein (Cand1), and unknown PS1145 targets sensitize cancer cells to CRL inhibition." (PMID 27906189, 2016). "In addition, high expression of CAND1 plays pro‐oncogenic roles in a variety of cancers." (PMID 37837399, 2023). "On the other hand, CAND1 (Cullin-associated neural-precursor-cell-expressed developmentally down-regulated 8 (NEDD8) dissociated protein 1 (CAND1)), a regulator of cullin-RING (a fascinating novel gene) ubiquitin ligases (CRLs), is implicated in the development of cancer resistance." (PMID 36456979, 2022). "We also find that we are able to successfully transfer our cancer models to tumour-adjacent tissue when inspecting the top 6 genes explained by CNVs (i.e. LLPH, YEATS4, UQCRFS1, POP4, CNOT2, and CAND1)." (PMID 40041206, 2025). "Moreover, one has to consider that the growth promoting effects of miR-148a overexpression described by Murata and colleagues may not only involve Cand1, but conceivably, other signaling pathways like PTEN-inhibited PI-3K/AKT (data not shown), also known to have pleotropic effects in cancer." (PMID 32059441, 2020).
tumor (5 papers, 2019 to 2025). "Overall, these results demonstrate that CAND1 promotes HCC cell proliferation, colony formation, migration, and invasion in vitro and that CAND1 deficiency impairs subcutaneous tumour formation and metastasis in vivo." (PMID 37837399, 2023). "In line with clinical findings, in vitro experiments in different PCa cell lines revealed that knockdown of Cand1 reduced cell viability and proliferation and increased apoptosis, therefore underlining its role in tumor progression." (PMID 32059441, 2020). "Furthermore, we observed that the expression level of CAND1 was positively associated with tumour diameter, vascular invasion, and TNM stage in HCC patients." (PMID 37837399, 2023). "In addition, high Cand1 levels were associated with higher Gleason Scores, as well as higher tumor recurrence and decreased overall survival." (PMID 32059441, 2020). "Furthermore, intrasplenic injection of CAND1 knockdown Hep3B cells led to fewer liver tumour nodules than injection of shNC cells, while tail vein injection of CAND1 knockdown Hep3B cells caused significantly fewer tumour nodules in the lung than injection of shNC cells." (PMID 37837399, 2023). "Knockdown of CAND1 inhibited the growth of subcutaneous tumours in mice, while overexpression of hnRNPA2B1 partially reversed the inhibitory effect of CAND1 on tumour growth." (PMID 37837399, 2023). "Subcutaneous tumours derived from CAND1 knockdown cells in a xenograft nude mouse model also exhibited downregulation of FASN, ACC1 and ACLY, enhanced oil red O staining and an increase in TAG content." (PMID 37837399, 2023). "CAND1 knockdown significantly delayed Hep3B cells from forming subcutaneous tumours in nude mice and CAND1 knockdown tumours exhibited reduced Ki‐67 staining compared to shNC tumours." (PMID 37837399, 2023). "Out of four published studies analyzed, three displayed an association between relapse-free survival (GSE70768, GSE70769, TGCA) and overall survival (OS) (GSE16560) after primary tumor resection and high Cand1 mRNA expression." (PMID 32059441, 2020). "Moreover, we verified that hnRNPA2B1 mediated CAND1 function in tumour progression and lipid metabolism." (PMID 37837399, 2023). "However, the mechanism by which CAND1 contributes to tumour progression and lipid metabolism through the SCF complex remains elusive." (PMID 37837399, 2023). "However, little research has been performed to determine the mechanism by which CAND1 promotes tumour progression and lipid synthesis through the SCF complex." (PMID 37837399, 2023). "Fatostatin obviously reversed the effect of CAND1 on cellular proliferation which suggests that CAND1 may promote tumour cell proliferation by regulating lipid synthesis." (PMID 37837399, 2023). "Moreover, the significant upregulation of CAND1 in neoplasm histologic grade 3 compared to grades 2 and 1 supports our previous observation that CAND1 correlates with worse prognosis in ERα-positive breast cancer." (PMID 36292029, 2022). "The next step was to investigate the potential impact of Cand1 in tumor recurrence and OS." (PMID 32059441, 2020). "Intratumoral injection of AAV‐shCAND1 potently downregulated CAND1 expression inhibited tumour growth, and decreased tumour volume without altering of mouse body weight." (PMID 37837399, 2023). "The reason for the elevated expression of CAND1 in tumours has not been previously reported." (PMID 37837399, 2023).
brain disorder (1 paper, 2020). A disease affecting the brain or part of the brain. "Four genes, ZYG11B, HECTD1, CAND1, and MYCBP2, ranked second, fourth, seventh and tenth, are all involved in protein ubiquitination, which has been implicated in neuronal function and brain disorders, including ASD." (PMID 33133139, 2020).
infection (1 paper, 2024). The state of being infected such as from the introduction of a foreign agent such as serum, vaccine, antigenic substance or organism. "Taken together, these findings suggest that CAND1 is indeed a physiological target of OspG through its kinase activity during infection." (PMID 38719850, 2024).
CAND1 also shares sentences with these, for which no sentence is quoted: lymph node metastasis (2 papers); non-small cell lung carcinoma (2); adenocarcinoma (1); atherosclerosis (1); cervical cancer (1); dementia (1); diabetic mellitus type 2 (1); endometrioid endometrial adenocarcinoma (1); Hypertension (1); lung adenocarcinoma (1); metastatic prostate carcinoma (1); Obesity (1).